MISP (mitotic spindle positioning)
Description:
Plays a role in mitotic spindle orientation and mitotic progression. Regulates the distribution of dynactin at the cell cortex in a PLK1-dependent manner, thus stabilizing cortical and astral microtubule attachments required for proper mitotic spindle positioning. May link microtubules to the actin cytospkeleton and focal adhesions. May be required for directed cell migration and centrosome orientation. May also be necessary for proper stacking of the Golgi apparatus.
Synonyms: C19orf21; DKFZp686H18209; Caprice; MISP1
Tractability: Antibody: its Gene Ontology location is reachable by antibodies, with high confidence; the Human Protein Atlas places it where antibodies can reach. PROTAC: ubiquitination databases record sites on it.
Gene: Protein-coding gene on chromosome 19 (748,404 to 764,363, forward strand). Ensembl gene ENSG00000099812.
Subcellular location: Cell junction, focal adhesion; Cytoplasm, cytoskeleton; Cytoplasm, cell cortex
Subcellular location (Human Protein Atlas): Focal adhesion sites; Plasma membrane
Gene Ontology:
Molecular function: actin filament binding; protein binding
Biological process: astral microtubule organization; cell migration; cortical actin cytoskeleton organization; establishment of centrosome localization; establishment of mitotic spindle orientation; mitotic spindle assembly; organelle localization
Cellular component: actin filament; cortical actin cytoskeleton; focal adhesion; mitotic spindle astral microtubule end; plasma membrane; spindle pole centrosome; cell cortex; cytoskeleton
Genetic constraint (gnomAD): Loss-of-function variants: 52 observed, 51.4 expected, observed/expected ratio (o/e) 1.01, 90% interval 0.81 to 1.27. The upper end of that interval is the gene's LOEUF score, 1.27, which puts it in group 5 of 6, group 1 being the genes least tolerant of losing a copy. Missense variants: 1,084 observed, 949.36 expected, observed/expected ratio (o/e) 1.14, 90% interval 1.09 to 1.2. Synonymous variants: 444 observed, 396.39 expected, observed/expected ratio (o/e) 1.12, 90% interval 1.04 to 1.21.
Homologues: Orthologues: chimpanzee MISP (98% identical), macaque MISP (90% identical), pig MISP (63% identical), mouse Misp (62% identical), rat Misp (60% identical), guinea pig Misp (54% identical), dog MISP (51% identical), tropical clawed frog misp (20% identical). Paralogues in human: MISP3 (10% identical).
Diseases named in the same sentence as MISP in open-access papers:
MISP is named in the same sentence as 30 diseases in open-access papers, as found by Europe PMC text mining. Sharing a sentence is not in itself a finding about the gene and the disease. The quoted sentences say what the papers report.
gastric cancer (6 papers, 2021 to 2025). A primary or metastatic malignant neoplasm involving the stomach. "In conclusion, MISP is overexpressed in gastric cancer, being associated with an intestinal phenotype in gastric carcinogenesis and having a role in cellular proliferation." (PMID 38785491, 2024). "It is involved in MISP‐mediated spindle formation and cytokinesis of gastric cancer cells in the middle and late stages of mitosis." (PMID 39949984, 2025). "MISP was detected on the membrane in 83% of the cases, being overexpressed in gastric cancer compared to normal gastric mucosa (n = 10)." (PMID 38785491, 2024). "The goal of this work was to evaluate the expression and clinical relevance of MISP in gastric cancer." (PMID 38785491, 2024). "We further analyzed the impact of downregulating MISP expression in two gastric carcinoma cell lines." (PMID 38785491, 2024). "Additionally, in vitro silencing of MISP led to a significant decrease in the viability of gastric carcinoma cells." (PMID 38785491, 2024). "Furthermore, when we silenced MISP in vitro, a significant decrease in the viability of gastric carcinoma cells was observed." (PMID 38785491, 2024). "In gastric cancer, SHCBP1 interacts with PLK1 to enhance MISP phosphorylation, regulating trastuzumab sensitivity." (PMID 40799237, 2025). "In gastric cancer, after stimulation by EGF, SHCBP1 is translocated into the nucleus and binds to PLK1 to promote the phosphorylation of MISP." (PMID 40799237, 2025).
colitis (3 papers, 2024 to 2025). Inflammation of the colon. "Therefore, a thorough analysis of MISP function in colitis-induced colorectal tumorigenesis at the cellular level indicates that MISP is a risk factor for CRC." (PMID 38474305, 2024). "Moreover, they showed that, in a Dextran Sulfate Sodium (DSS)-induced colitis mouse model, MISP deficiency led to exacerbated inflammation and decreased cell proliferation in the crypts, which revealed its role in protecting against colitis." (PMID 38785491, 2024). "Notably, MISP-deficient mice showed reduced colon tumor formation in the AOM/DSS-induced colitis model." (PMID 38474305, 2024). "MISP is found on the apical membrane of the intestinal mucosa and helps stabilize and elongate microvilli, offering protection against colitis." (PMID 38474305, 2024). "This study explored the role of MISP in colorectal tumorigenesis using a database, human CRC cells, and a mouse model for colitis-induced colorectal tumors triggered by azoxymethane (AOM)/dextran sodium sulfate (DSS) treatment." (PMID 38474305, 2024). "MISP is found on the apical membrane of the colon, and its absence has been shown to aggravate DSS-induced colitis." (PMID 38474305, 2024). "While colitis is a known risk factor for CRC, the connection between MISP and CRC has not yet been explored." (PMID 38474305, 2024). "In a mouse model induced by sulfated polysaccharide, MISP plays a role in the recovery of the colon after inflammation through its anti-inflammatory and proliferative effects, and a lack of MISP exacerbates colitis in mice, which may be a new therapeutic target for treating IBD." (PMID 38814387, 2025).
colorectal cancer (2 papers, 2024). A primary or metastatic malignant neoplasm that affects the colon or rectum. "In the HCT116 human colorectal cancer cell line, we detected a substantial alteration in the expression levels of a total of 70 genes upon MISP knockdown compared to the control group." (PMID 38474305, 2024). "Similarly, in human colorectal cancer (CRC) cell lines, the knockdown of MISP significantly diminishes the colony-forming ability, suggesting that MISP promotes CRC cell proliferation." (PMID 38785491, 2024).
esophageal cancer (2 papers, 2017 to 2022). A primary or metastatic malignant neoplasm involving the esophagus. "Five nucleoproteins MISP, KLF10, KLF15, PPP1R18, and RXRβ were identified by oligonucleotide trapping, as the binding factors on the TRE under TPA stimulation, and were expressed at varying expression levels in esophageal cancer." (PMID 29098164, 2017). "Several nucleoproteins (MISP, KLF10, KLF15, PPP1R18, and RXRβ) have been identified by affinity chromatography and mass spectrometry and could respond to TPA stimulation and regulate LCN2 expression in esophageal cancer cells." (PMID 29098164, 2017).
gastric adenocarcinoma (2 papers, 2022 to 2024). "Another major finding of our study was the association of MISP expression with the intestinal phenotype, evidenced by a higher expression of MISP in the preneoplastic lesion IM and, also, in intestinal-type gastric adenocarcinoma." (PMID 38785491, 2024). "MISP expression was evaluated by immunohistochemistry in a single hospital series (n = 286) of gastric adenocarcinomas and compared with normal gastric mucosa and intestinal metaplasia, a preneoplastic lesion." (PMID 38785491, 2024).
pancreatic cancer (2 papers, 2022 to 2024). "In pancreatic cancer, MISP has been associated with cell migration and epithelial–mesenchymal transition (EMT)." (PMID 38785491, 2024). "MISP expression was significantly higher in pancreatic cancer tissues compared to normal pancreas tissues, which was associated with a poor prognosis." (PMID 35433491, 2022). "However, the expression and function of MISP in human pancreatic cancer are still unclear." (PMID 35433491, 2022).
pancreatic ductal adenocarcinoma (2 papers, 2024). An infiltrating adenocarcinoma that arises from the epithelial cells of the pancreas. "Reducing MISP expression also inhibits cell proliferation in pancreatic ductal adenocarcinoma cells." (PMID 38474305, 2024). "Concordantly, reducing MISP expression in pancreatic ductal adenocarcinoma cells results in inhibited cell proliferation." (PMID 38785491, 2024).
cholangiocarcinoma (1 paper, 2024). A carcinoma that arises from the intrahepatic biliary tree (intrahepatic cholangiocarcinoma) or from the junction, or adjacent to the junction, of the right and left hepatic ducts (hilar cholangiocarcinoma). "In another study, the in vitro knockdown of MISP in cholangiocarcinoma cells resulted in reduced trans-lymphatic endothelial migration and impaired wound healing, alongside alterations in focal adhesions." (PMID 38785491, 2024).
colon cancer (1 paper, 2024). "We found that MISP was highly expressed in colon cancer patient tissues and that reduced MISP expression inhibited cell proliferation." (PMID 38474305, 2024).
colorectal tumor (1 paper, 2024). "In conclusion, MISP enhances colorectal tumorigenesis through its interaction with OIP5 and stimulates colorectal tumor growth by upregulating the levels of phosphorylated STAT3 in the JAK2-STAT3 signaling pathway." (PMID 38474305, 2024).
inflammatory bowel disease (1 paper, 2024). A spectrum of small and large bowel inflammatory diseases of unknown etiology. "Such indications hint at the potential of MISP as a novel therapeutic target for inflammatory bowel disease (IBD)." (PMID 38785491, 2024).
lung carcinoma (1 paper, 2025). "Similarly, deficiency of MST1/2 kinases restored cell death, lipid peroxidation, and ferroptosis caused by MISP depletion in lung cancer cells." (PMID 40019375, 2025). "Both MISP mRNA and protein levels were dramatically increased in lung cancer tissues, and elevated MISP predicted worse clinical outcomes in patients with lung cancer." (PMID 40019375, 2025). "In clinical samples of lung cancer, a noteworthy positive correlation was observed among the expression levels of MISP, CYR61, and CTGF." (PMID 40019375, 2025). "In our study, MISP was identified as a critical driver of ferroptosis resistance that facilitates lung cancer cell proliferation, consistent with its significant upregulation in lung cancer tissues." (PMID 40019375, 2025). "We discovered that MISP was significantly upregulated in lung cancers relative to adjacent counterparts, and was correlated with shorter patient survival and disease‐free times." (PMID 40019375, 2025). "We found that the Hippo signaling pathway, which is crucial for cell proliferation and tissue homeostasis, showed a positive correlation with higher MISP expression in lung cancer patients, as evidenced by Gene Set Enrichment Analysis (GSEA)." (PMID 40019375, 2025). "To elucidate the mechanisms through which MISP inhibits ferroptosis, we conducted an analysis of lung cancer tissue transcript datasets from The Cancer Genome Atlas (TCGA) to identify potential signaling pathways and key genes that connect MISP to ferroptosis." (PMID 40019375, 2025). "This study explores the role of Mitotic Spindle Positioning (MISP) as a key inhibitor of ferroptosis in non‐small cell lung cancer (NSCLC)." (PMID 40019375, 2025). "Given that the Hippo pathway senses various intrinsic and extrinsic cues, such as serum starvation and cell density, we observed that lung cancer cells, when subjected to serum deprivation followed by serum recovery, exhibited a marked increase in MISP and YAP targets." (PMID 40019375, 2025). "Given that targeting ferroptosis is a potential strategy to enhance targeted or immunotherapy, it is not clear whether MISP is implicated in regulation of lung cancer immune microenvironment, which should be an interesting work in the future." (PMID 40019375, 2025). "Taken together, the data here demonstrate that MST1/2 kinases are indispensable for MISP to activate YAP and promote tumor growth in lung cancer." (PMID 40019375, 2025). "This underscores the significance of MST1/2 kinases in the MISP‐mediated regulation of YAP and highlights their potential as therapeutic targets in lung cancer treatment." (PMID 40019375, 2025).
tumor (10 papers, 2018 to 2025). "It has been reported that increases in MISP are associated with decreased cell proliferation and expression of immune checkpoint molecules (resulting in tumor growth) and increased gene mutation burden." (PMID 38474305, 2024). "In agreement with its tumor‐promoting role in vitro, MISP loss in H1395 cells greatly repressed tumor growth in nude mice, as evidenced by smaller tumor weight and diminished Ki‐67 reactivity in MISP‐deficient xenografts." (PMID 40019375, 2025). "We further confirmed the mRNA expression of PLK1 and MISP in five iCCA tumor samples and their adjacent normal liver tissues." (PMID 38057358, 2024). "The ATAC-seq tracks from the genome datasets showed high chromatin-accessible regions in the promoters of PLK1 and MISP in tumor tissues, consistent with the ATAC-seq analysis." (PMID 38057358, 2024). "Taken together, the results revealed that the cell cycle regulator PLK1 and its substrate MISP promoted lymphatic invasion and tumor growth and repressed E-cadherin adherens junctions, demonstrating the crucial role of PLK1 and MISP in iCCA aggressiveness." (PMID 38057358, 2024). "In iCCA, PLK1 and MISP promote aggressiveness by increasing lymphatic invasion, tumor growth, and motility through the repression of E-cadherin adherens junctions." (PMID 38057358, 2024). "Heatmap analysis of cell cycle gene expression showed increased expression of PLK1 (polo-like kinase 1) and its substrate MISP (mitotic spindle positioning) in iCCA tumor samples." (PMID 38057358, 2024). "Increased expression of PLK1 and MISP was significantly correlated with tumor number, N stage, and lymphatic invasion in an iCCA cohort." (PMID 38057358, 2024). "Increased expression of PLK1 and MISP correlated with higher risks of tumor number, N stage, and lymphatic invasion in late-stage iCCA patients and with poor prognosis." (PMID 38057358, 2024). "Notably, elevated levels of MISP were found to be significantly correlated with specific tumor classifications according to the Laurén classification system." (PMID 38785491, 2024). "The role of PLK1 and MISP in regulating tumor cell adhesive functions remains to be determined." (PMID 38057358, 2024). "We wanted to confirm the role of PLK1 and MISP in the tumor growth of iCCA cells." (PMID 38057358, 2024). "In this study, we identified the upregulation of PLK1 and MISP in CCA patient tumor tissues and further uncovered the mechanism by which PLK1 and MISP mediate lymphatic invasion in iCCA." (PMID 38057358, 2024). "Compared with the normal group, the tumor group had higher expressions of MLPH, MISP, KDM6B, and FXYD3 genes." (PMID 35673567, 2022). "In this study, we hypothesized that MISP promotes the development of CRC and investigated the relationship between MISP and intestinal tumorigenesis by evaluating tumor development induced by colitis in Misp KO mice using the AOM/DSS model." (PMID 38474305, 2024). "Targeting either the MISP/IQGAP1 or the Cdc42/IQGAP1 interaction may decrease the amount of active Cdc42 in cancer cells and thereby prevent tumor progression." (PMID 29679050, 2018). "However, the role of MISP in tumor lymphatic invasion and EMT has not been demonstrated." (PMID 38057358, 2024). "Furthermore, MISP has been reported to interact with and regulate IQ motif containing GTPase activating protein 1 (IQGAP1), a protein that plays a vital role in the progression of PDAC by facilitating epithelial-mesenchymal transition (EMT) and affecting the tumor microenvironment." (PMID 35433491, 2022).
cancer (9 papers, 2018 to 2025). A tumor composed of atypical neoplastic, often pleomorphic cells that invade other tissues. "MISP is associated with the actin cytoskeleton and focal adhesions and has been functionally linked with cytokinesis and directed cancer cell migration." (PMID 38785491, 2024). "The depletion of MISP in cancer cell lines causes mitotic arrest, impairs the proper mitotic spindle positioning and orientation, and reduces cell migration." (PMID 38785491, 2024). "The mitotic spindle positioning (MISP) protein has the function of correcting mitotic spindle positioning and centrosome clustering and has been implicated in the cytokinesis and migration of cancer cells." (PMID 38785491, 2024). "MISP was first identified in a genome-wide RNAi screen as a protein involved in centrosomal clustering in cancer cells with extra centrosomes." (PMID 38785491, 2024). "Despite the links with these cancer cell features, the expression and function of MISP in cancer are largely unexplored." (PMID 38785491, 2024). "Furthermore, extracellular vesicles derived from macrophages were shown to activate STAT3 phosphorylation by downregulating MISP, thereby promoting therapeutic resistance in cancer cells." (PMID 40428339, 2025). "Nevertheless, the role of MISP in cancer is far from being understood." (PMID 38785491, 2024). "Therefore, the observed interaction between MISP, IQGAP1, and Cdc42 sheds light on potential mechanisms underlying cancer progression, highlighting promising avenues for further investigation and therapeutic intervention." (PMID 38785491, 2024). "We can speculate that MISP expression in cancer is important to overcome chromosome number aberrations and allow mitosis to occur." (PMID 38785491, 2024). "Based on three microarray gene profiling datasets from the Gene Expression Omnibus (GEO) and RNA-Seq expression data from The Cancer Genome Atlas (TCGA), Mitotic Spindle Positioning (MISP or C19orf21), a substrate of Plk1, was found to be up-regulated in many types of cancer." (PMID 35433491, 2022). "Blocking the formation of the MISP/IQGAP1/Cdc42 complex might have therapeutic potential for specific cancer types." (PMID 29679050, 2018). "Thus, it might be worth to further explore MISP function in cancer cell behavior and aggressiveness." (PMID 38785491, 2024). "Plk1 and its downstream targets, including mitotic spindle positioning (MISP), RhoGDI1, and FoxM1, regulate proliferative and invasive capabilities through epithelial-mesenchymal transition (EMT) transition in cancer cells." (PMID 40166466, 2025). "The expression of MISP, CHMP2B, IL-18, TMSB4X, and EFEMP1 proteins in carcinoma tissue was higher than that in para-carcinoma tissues." (PMID 38835670, 2024). "Initially, we confirmed MISP expression levels in colorectal tissues from both healthy individuals and CRC patients (including primary tumors and adjacent normal tissues), utilizing the TCGA cancer genome database." (PMID 38474305, 2024).
colorectal (1 paper, 2024). "In the future, further exploration of the roles of MISP and TGF-β1, along with EMT, in CRC could lead to a deeper understanding of the mechanisms underlying MISP-driven colorectal tumorigenesis." (PMID 38474305, 2024).
infection (1 paper, 2023). The state of being infected such as from the introduction of a foreign agent such as serum, vaccine, antigenic substance or organism. "Four additional infection-induced proteolytic cleavage sites identified in BCAP31, LASP1, MISP, and TRIM28 were consistent with the sequence specificity of 3CLpro." (PMID 37240067, 2023).
MISP also shares sentences with these, for which no sentence is quoted: hepatocellular carcinoma (2 papers); cervical squamous cell carcinoma (1); colon adenocarcinoma (1); diabetes (1); endocervical adenocarcinoma (1); esophageal squamous cell carcinoma (1); head and neck squamous cell carcinoma (1); intrahepatic cholangiocarcinoma (1); lung adenocarcinoma (1); ovarian serous cystadenocarcinoma (1); rectum adenocarcinoma (1); thyroid carcinoma (1); uterine carcinosarcoma (1); uterine corpus endometrial carcinoma (1).